SNORA51 (small nucleolar RNA, H/ACA box 51)
Synonyms: ACA51
Gene: Small nucleolar RNA gene on chromosome 20 (2,655,067 to 2,655,198, forward strand). Ensembl gene ENSG00000271798.
Gene Ontology:
Biological process: RNA processing
Cellular component: nucleolus
Homologues: Orthologues: chimpanzee SNORA51 (100% identical), macaque SNORA51 (99% identical), guinea pig SNORA51 (92% identical).
Diseases named in the same sentence as SNORA51 in open-access papers:
SNORA51 is named in the same sentence as 5 diseases in open-access papers, as found by Europe PMC text mining. Sharing a sentence is not in itself a finding about the gene and the disease. The quoted sentences say what the papers report.
breast carcinoma (1 paper, 2025). "In breast cancer, increased snoRA51 expression was connected to worse prognosis, overall survival, and disease-free survival." (PMID 41510246, 2025).
colon cancer (1 paper, 2025). "snoRA51 is also upregulated in colon cancer and hepatocellular carcinoma (HCC) and is defined as a potential biomarker." (PMID 41510246, 2025).
cancer (1 paper, 2025). A tumor composed of atypical neoplastic, often pleomorphic cells that invade other tissues. "SnoRNAs with elevated expression in GSC and GBM lines (snoRA38, snoRA51, snoRA71, and snoRA75) have been previously implicated in cancer development." (PMID 41510246, 2025). "In addition, snoRA51 enhanced cancer stem cell-like properties via the RPL3/NPM1/c-MYC pathway." (PMID 41510246, 2025).
SNORA51 also shares sentences with these, for which no sentence is quoted: hepatocellular carcinoma (1 paper); tumor (1).